MYCT1 (MYC target 1)
Description:
May regulate certain MYC target genes, MYC seems to be a direct upstream transcriptional activator. Does not seem to significantly affect growth cell capacity. Overexpression seems to mediate many of the known phenotypic features associated with MYC, including promotion of apoptosis, alteration of morphology, enhancement of anchorage-independent growth, tumorigenic conversion, promotion of genomic instability, and inhibition of hematopoietic differentiation (By similarity).
Synonyms: MTLC; FLJ21269
Tractability: No criterion of Open Targets' tractability assessment is met for any kind of drug.
Gene: Protein-coding gene on chromosome 6 (152,697,897 to 152,724,569, forward strand). Ensembl gene ENSG00000120279.
Subcellular location: Nucleus
Subcellular location (Human Protein Atlas): Nucleoplasm; Nuclear bodies; Vesicles
Gene Ontology:
Cellular component: nucleoplasm; nucleus
Genetic constraint (gnomAD): Loss-of-function variants: 12 observed, 13.38 expected, observed/expected ratio (o/e) 0.9, 90% interval 0.57 to 1.45. The upper end of that interval is the gene's LOEUF score, 1.45, which puts it in group 5 of 6, group 1 being the genes least tolerant of losing a copy. Missense variants: 242 observed, 247.59 expected, observed/expected ratio (o/e) 0.98, 90% interval 0.88 to 1.09. Synonymous variants: 87 observed, 90.92 expected, observed/expected ratio (o/e) 0.96, 90% interval 0.8 to 1.14.
Homologues: Orthologues: chimpanzee MYCT1 (98% identical), macaque MYCT1 (97% identical), pig MYCT1 (80% identical), dog MYCT1 (78% identical), rabbit MYCT1 (72% identical), rat Myct1 (70% identical), mouse Myct1 (68% identical), guinea pig MYCT1 (63% identical), tropical clawed frog myct1 (56% identical), zebrafish myct1a (33% identical), zebrafish myct1b (22% identical).
Diseases named in the same sentence as MYCT1 in open-access papers:
MYCT1 is named in the same sentence as 25 diseases in open-access papers, as found by Europe PMC text mining. Sharing a sentence is not in itself a finding about the gene and the disease. The quoted sentences say what the papers report.
laryngeal carcinoma (14 papers, 2011 to 2025). Carcinoma that arises from the laryngeal epithelium. "In order to find the key DEGs downstream of MYCT1 associated with laryngeal cancer migration and metastasis, we first identified the DEGs in HNSCC by data mining." (PMID 33680912, 2020). "MYCT1, a target of c-Myc, inhibits laryngeal cancer cell migration, but the underlying mechanism remains unclear." (PMID 33680912, 2020). "In a previous study, we found several differentially expressed genes related to the occurrence and development of lymphogenic malignant diseases in laryngeal cancer cells stably transformed with MYCT1, including RUNX1 (runt related protein 1)." (PMID 38172714, 2024). "Previously, we discovered that MYCT1 interacted with MAX (MYC associated Factor X, MAX) in laryngeal carcinoma." (PMID 38172714, 2024). "The following year, another study found that MYCT1 significantly decreases the expression of miR-629-3p but increased the expression of ESRP2 in laryngeal cancer cells." (PMID 35803984, 2022). "In the study, we detected differentially expressed genes (DEGs) from laryngeal cancer cells transfected by MYCT1 using RNA-seq (GSE123275)." (PMID 33680912, 2020). "We also found that both COL6A2 and COL6A3 knockdown significantly recued the effects of MYCT1 silence on their expressions in laryngeal cancer cells (P < 0.01), respectively." (PMID 33680912, 2020). "COL6A2 and COL6A3 knockdown significantly recued the effects of MYCT1 silence on the adhesion, migration and wound healing abilities of the laryngeal cancer cells (P < 0.01), respectively." (PMID 33680912, 2020). "MYCT1 knockdown and overexpression significantly increased and decreased the adhesion, migration and wound healing abilities of the laryngeal cancer cells compared with controls (P < 0.01), respectively." (PMID 33680912, 2020). "YY1 promotes migration, proliferation and suppression of apoptosis in laryngeal cancer via directly inhibiting MYCT1, which can be used as target to prevent the progression of laryngeal cancer." (PMID 33344262, 2020). "Similar to our RNA-seq results, we confirmed that COL6 is a target of MYCT1 in laryngeal cancer cells." (PMID 33680912, 2020). "In MYCT1-overexpressing laryngeal cancer cells, another 13 DEGs (GSE123275) were overlapped in the GSE6631 and TCGA datasets, where COL6A1, COL6A2, and COL6A3 were also present." (PMID 33680912, 2020). "The DEGs overlapped between GSE6631and TCGA datasets were then compared with ours to find the key DEGs downstream of MYCT1 related to the adhesion and migration of laryngeal cancer cells." (PMID 33680912, 2020). "Recently, we obtained lots of differentially expressed genes (DEGs) downstream of MYCT1 in laryngeal cancer by transcriptome sequencing (GSE123275)." (PMID 33680912, 2020). "These indicate that COL6 is a potential target of MYCT1 and participates the adhesion and migration of laryngeal cancer cells, which provides an important clue for further study on how MYCT1 regulating COL6 in laryngeal cancer progression." (PMID 33680912, 2020). "We also found that MYCT1 is a down-regulated and suppress cancer cell migration in laryngeal cancer, suggesting that it acts as tumor suppressor." (PMID 33680912, 2020). "At the protein level, Collagen VI was significantly upregulated and downregulated in siMYCT1- and MYCT1-transfected laryngeal cancer cells compared with controls (P < 0.01), respectively." (PMID 33680912, 2020). "In the study, we also found that MYCT1 inhibits laryngeal cancer cell adhesion and migration and the effects are rescued by Collagen VI." (PMID 33680912, 2020). "MYCT1 was significantly decreased and increased both at mRNA and protein levels in laryngeal cancer cells transfected with siMYCT1 and MYCT1 compared with controls (P < 0.01), respectively, suggesting that transfection is successive." (PMID 33680912, 2020). "Previously, we discovered that MYCT1 suppresses laryngeal cancer cell migration through the CREB/MYCT1/NAT10 axis." (PMID 33680912, 2020).
laryngeal carcinoma (continued). "In our RNA-seq results, COL6A1, COL6A2, and COL6A3 were downregulated at mRNA levels in MYCT1 overexpressing laryngeal cancer cells (GSE123275)." (PMID 33680912, 2020). "In the previous study, we first cloned MYCT1 in laryngeal cancer, named as c-Myc target from laryngeal cancer (MTLC)." (PMID 33680912, 2020). "Taken together with the negative correlation between YY1 and MYCT1 mRNA levels, these results indicate that YY1 directly and negatively regulates MYCT1 transcription activity in laryngeal cancer." (PMID 28485541, 2017). "We also found that MYCT1 promoter region including C‐MYC binding site is hypermethylated in laryngeal cancer, suggesting that the methylation status interferes with the binding of C‐MYC to MYCT1 leading to MYCT1 dysregulation in laryngeal cancer." (PMID 28485541, 2017). "We also found that YY1 and MYCT1 are upregulated and downregulated in laryngeal cancer, respectively, implying that both genes participate in laryngeal carcinogenesis." (PMID 28485541, 2017). "Statistically, YY1 and MYCT1 were significantly upregulated and downregulated at transcriptional level in laryngeal cancer tissues compared to matched normal tissues, respectively (P < 0.05)." (PMID 28485541, 2017). "Real‐time RT‐PCR results indicated that high YY1 and low MYCT1 mRNA levels in laryngeal cancer tissues were observed in 19 of 30 (63.33%) and 24 of 30 (80%) cases, respectively." (PMID 28485541, 2017). "YY1 silence had similar biological functions as MYCT1 overexpression in repressiveness of proliferation and migration, and promotion of apoptosis in laryngeal cancer cells." (PMID 28485541, 2017). "The present study focused on the epigenetic alterations leading to transcriptional down-regulation of MYCT1, thereby opening a new avenue to understand the molecular pathways in laryngeal cancer and to develop potential therapeutics against laryngeal cancer." (PMID 22672838, 2012). "To confirm that the aberrant methylation of MYCT1 induced transcriptional down-regulation, we compared its mRNA levels in laryngeal carcinoma Hep2 cells to Hep2 cells treated with the inhibitor of the methylase enzyme 5-aza." (PMID 22672838, 2012). "We also found that MYCT1 inhibited the adhesion and migration of laryngeal cancer cells via COL6." (PMID 33680912, 2020). "Furthermore, YY1 contributes to the tumorigenesis and progression in laryngeal cancer by directly regulating MYCT1." (PMID 32943988, 2020). "We also found that high level of YY1 and low level of MYCT1 in laryngeal cancer tissues are correlated with metastasis, suggesting that both YY1 and MYCT1 genes might take part in laryngeal cancer progression." (PMID 28485541, 2017). "Taken together, we speculate that YY1 plays a potentially oncogenic role via directly inhibiting MYCT1 expression in laryngeal cancer genesis and progression." (PMID 28485541, 2017). "Next, how MYCT1 functions in laryngeal cancer development is a key issue to be solved." (PMID 28485541, 2017). "In our previous study, we obtained series of differentially expressed genes using MYCT1 cDNA array assay (data not shown), which will help us to further study the molecular mechanism of MYCT1 in regulation of laryngeal cancer cell proliferation, migration, and apoptosis in the future." (PMID 28485541, 2017). "In this study, we assessed YY1 and MYCT1 expression in laryngeal cancer tissues." (PMID 28485541, 2017). "In addition, laryngeal cancer cell migration was reported to be promoted by the MYCT1/NAT10 axis." (PMID 34362389, 2021). "MYCT1 (MYC target 1), located on chromosome 6q25, was first discovered and cloned by our research group in laryngeal cancer and was once named the C-MYC target from laryngeal cancer cells (MTLC)." (PMID 38172714, 2024). "At the mRNA level, Knockdown of MYCT1 significantly increased the COL6A1, COL6A2, and COL6A3 expression but MYCT1 decreased the COL6A2, and COL6A3 expression in laryngeal cancer cells (P < 0.01), respectively." (PMID 33680912, 2020).
laryngeal carcinoma (continued). "Similar to MYCT1 overexpression and contrary to MYCT 1 silence, YY1 knockdown significantly decreased laryngeal cancer cell proliferation (P < 0.05) and cloning formation compared to the control (P < 0.05)." (PMID 28485541, 2017). "In the study, we confirmed that MYCT1 is a novel target of YY1 and is negatively regulated by YY1 in laryngeal cancer." (PMID 28485541, 2017). "YY1 promotes proliferation and migration with suppression of apoptosis via directly inhibiting MYCT1 in laryngeal cancer cells, suggesting that YY1 is a useful target as a potential oncogene in laryngeal cancer development and progression." (PMID 28485541, 2017). "Contrary to MYCT1 knockdown, YY1 knockdown and MYCT1 overexpression significantly increased laryngeal cancer cell apoptosis compared to the control (P < 0.05)." (PMID 28485541, 2017). "YY1 promotes proliferation, migration with suppression of apoptosis via directly inhibiting MYCT1 in laryngeal cancer, suggesting that YY1 is a useful target as a potential oncogene in laryngeal cancer development and progression." (PMID 28485541, 2017). "Therefore, we speculate that YY1 functions in laryngeal cancer probably via MYCT1." (PMID 28485541, 2017). "MYCT1, which was previously named MTLC (c-Myc target from laryngeal cancer cells, GenBank access number AF527367), was cloned by our team in 2003." (PMID 22672838, 2012). "Moreover, MYCT1 has also been reported to inhibit EMT and the migration of laryngeal cancer cells via the SP1/miR-629-3p/ESRP2 pathway." (PMID 37587470, 2023). "Later on, a study published after the date of the annotation files we used to train our models, suggested that MYCT1 synergistically interact with MAX as a co-transcription factor or a component of MAX transcriptional complex, involved in enhanced apoptosis in laryngeal cancer cells." (PMID 35803984, 2022). "Therefore, we plan to focus on the following two issues in future studies: 1) regulatory mechanism of MYCT1 on COL6; 2) molecular mechanism of COL6 in laryngeal cancer cell adhesion and migration." (PMID 33680912, 2020). "We also analyzed the relationships between YY1 or MYCT1 mRNA levels and metastasis in the cancer tissues from laryngeal cancer patients with or without lymphatic metastasis." (PMID 28485541, 2017). "Significantly higher expression of YY1 and lower expression of MYCT1 were found in laryngeal cancer tissues of patients with lymphatic metastasis than those without metastasis.YY1 directly bound to MYCT1 promoter region and inhibited its promoter activity." (PMID 28485541, 2017). "In the present study, we aim to identify DEGS downstream of MYCT1 through analyzing HNSCC gene expression data from the Gene Expression Omnibus (GEO) and The Cancer Genome Atlas (TCGA) together with ours, and explore their function in the adhesion and migration of laryngeal cancer cells." (PMID 33680912, 2020). "But MYCT1-mediated laryngeal cancer cell adhesion has not been reported." (PMID 33680912, 2020). "Real‐time RT‐PCR results also showed that YY1 and MYCT1 mRNA levels were significantly higher and lower in Hep2 cells than those in HEK293T cells (P < 0.05), respectively, further suggesting the negative correlation between YY1 and MYCT1 at transcription level in laryngeal cancer." (PMID 28485541, 2017). "YY1 and MYCT1 were upregulated and downregulated at transcriptional level in laryngeal cancer, respectively, which showed a negative correlation between YY1 and MYCT1 expression in laryngeal cancer." (PMID 28485541, 2017). "MYCT1 (Gene ID: 80177) is a novel candidate TSG cloned using in silicon hybridization and molecular methods from LSCC by our team, which was previously named MTLC (c-Myc target from laryngeal cancer cells, GenBank accession No. AF_527367)." (PMID 21998677, 2011).
laryngeal squamous cell carcinoma (4 papers, 2011 to 2025). A squamous cell carcinoma that arises from the larynx. "Myc target 1 (MYCT1), located at chromosome 6q25.2, is a candidate tumor suppressor gene initially identified in laryngeal squamous cell carcinoma." (PMID 39744435, 2025). "MYC target 1 (MYCT1), a direct target gene of c-Myc, is a novel candidate tumor suppressor gene first cloned from laryngeal squamous cell carcinoma." (PMID 30283340, 2018). "MYCT1, a putative target of c-Myc, is a novel candidate tumor suppressor gene cloned from laryngeal squamous cell carcinoma (LSCC)." (PMID 21998677, 2011). "MYC target 1 (MYCT1), also known as MTLC, is a direct target gene of c-Myc, and it has been first cloned from laryngeal squamous cell carcinoma (LSCC)." (PMID 30283340, 2018).
gastric carcinoma (3 papers, 2011 to 2020). A carcinoma that arises from epithelial cells of the stomach. "For example, downregulation of MYCT1 was observed in a majority of studied gastric carcinoma samples, in accordance of its ability to promote apoptosis of gastric carcinoma cell lines when overexpressed." (PMID 33041669, 2020). "As a novel candidate of tumor suppressor genes, MYCT1 has previously been found to be downregulated in gastric carcinoma (GC) and it plays an important role in regulating apoptosis and cell cycle process of GC cells." (PMID 30283340, 2018). "Our previously study demonstrated that MYCT1 existed in various human tissues and was down-regulated in gastric carcinoma tissues." (PMID 21998677, 2011). "Low expression of MYCT1 has been found in the tumor tissues of gastric carcinoma patients." (PMID 30283340, 2018). "It has been documented that MYCT1 can suppress cell growth and induce apoptosis in LSCC and gastric carcinoma cells." (PMID 30283340, 2018). "Since MYCT1 was cloned from LSCC and down-regulated in gastric carcinoma tissues, we are interested in exploring whether it is also down-regulated in LSCC and existed the expression differences between MYCT1-TV and MYCT1 in LSCC." (PMID 21998677, 2011).
Obesity (3 papers, 2022 to 2026). Accumulation of substantial excess body fat. "CERS6 and MYCT1 have been studied to be associated with obesity, weight gain, and subcutaneous fats in several mammalian species, including humans, mice, sheep, and pigs." (PMID 37229195, 2023). "In addition, rs17710008 (MYCT1) was associated with both obesity and diabetes [AORs = 3.55 (1.39–9.04), p = 0.008 and 2.55 (1.09–5.97), p = 0.031]." (PMID 36386790, 2022). "These genes (CERS6 and MYCT1) are mostly related to muscles, subcutaneous fat, and obesity in humans, mice, sheep, and pig’s meat, placing them in the list of possible candidate genes for carcass-related traits in beef cattle." (PMID 37229195, 2023). "Targeting MYCT1-IFITM2/3 may offer new therapeutic options for obesity and metabolic disorders." (PMID 41880193, 2026).
bladder cancer (2 papers, 2022 to 2023). "These factors suggest that JorA upregulating MYCT1 has a positive effect on the suppression of bladder cancer." (PMID 37587470, 2023). "NR4A3 and MYCT1 genes, whose expression was increased by JorA, were found to be lowly expressed in bladder cancer samples in clinical cases." (PMID 37587470, 2023).
hepatocellular carcinoma (2 papers, 2012 to 2025). A malignant tumor that arises from hepatocytes. "As a putative target of c-Myc, MYCT1 is expressed in the nuclei of human hepatocellular carcinoma cells, while a wide distribution of MYCT1 has been demonstrated in various tissues." (PMID 22672838, 2012).
cocaine addiction (1 paper, 2020). "Twelve DEGs (Myct1, Gm21860, Ninj2, Fam183b, Lars2, Alkbh1, Fgf5, Frmd7, Tm6sf2, Wnt6, Batf3, and Clca1) were found to be regulated inversely among the overlap genes, which may be possible targets of RPA to disrupt the cocaine addiction process." (PMID 32489401, 2020).
diffuse large B-cell lymphoma (1 paper, 2024). "This study finds that there is a MYCT1-MAX-RUNX1 signaling pathway in diffuse large B-cell lymphoma." (PMID 38172714, 2024). "MYCT1 was located in one of three smallest overlap regions of diffuse large B-cell lymphoma, it altered chromosomal instability of diffuse large B-cell lymphoma cells." (PMID 38172714, 2024). "In this study, we found MYCT1 could inhibit proliferation and promote cell cycle arrest in diffuse large B-cell lymphoma cells." (PMID 38172714, 2024). "MYCT1 may represses RUNX1 transcription by binding MAX in diffuse large B-cell lymphoma cells." (PMID 38172714, 2024).
keratinocyte carcinoma (1 paper, 2023). A skin cancer arising from the keratin-producing cells of the epidermis. "Using whole exome sequencing data, we performed groupwise tests for rare missense variants in our dataset and found robust associations (p < 10−6, Burden Zeggini test) between MC1R, EPHA8, EPO, MYCT1, ADGRG3, and MGME1 and keratinocyte cancer." (PMID 37444464, 2023).
liver cancer (1 paper, 2024). An epithelial or non-epithelial malignant neoplasm that arises from the liver. "Conversely, upregulated miR-34a-5p suppresses the invasion and metastasis of liver cancer by targeting the transcription factor YY1 to mediate MYCT1 upregulation." (PMID 38256049, 2024).
lung carcinoma (1 paper, 2016). "In addition, our work first identified Ala88, which mutates into aspartic acid (Asp) in a clinical lung cancer patient sample, contributed to the subcellular localization of MYCT1." (PMID 26710964, 2016).